MET (MET proto-oncogene, receptor tyrosine kinase)
Diseases named in the same sentence as MET in open-access papers (continued):
Sharing a sentence is not in itself a finding about the gene and the disease.
tumor (continued). "However, the inhibition of mTOR with an mTOR inhibitor (everolimus) reduced the tumor growth in xenograft mice, but did not shrink the tumor size, probably due to the increased activity of Akt and ERK by this drug, confirming the c-MET-dependent resistance of the tumor." (PMID 31416195, 2019). "No MET gene mutation or amplification was observed in the tumor analysis." (PMID 30474572, 2018). "Fluorescent in situ hybridization (FISH) for MET-amplification, immunohistochemistry (IHC) for MET- and ALK-expression, and Next Generation Sequencing (NGS) for concomitant driver mutations were performed on EGFR-mutated tumor samples from erlotinib-treated patients." (PMID 29899852, 2018). "In addition, one EGFR-mutated tumor exhibited MET-overexpression without MET-amplification, suggesting other mechanisms increasing the receptor expression in this case." (PMID 29899852, 2018). "Hepatocyte growth factor (HGF)/ mesenchymal-epithelial transition factor (c-MET) signaling is involved in complex cellular programs that are important for embryonic development and tissue regeneration, but its activity is also utilized by cancer cells during tumor progression." (PMID 30513872, 2018). "Furthermore, analyzing a platform of 20,981 tumor samples from The Cancer Genome Atlas (TCGA) in cBioportal Web resource online (cBioportal for Cancer Genomic) revealed that the amplification of MET gene accounted for a considerable part of alterations, especially in GC." (PMID 30158543, 2018). "Indeed, the HGF/c-MET system plays an essential role in tumor–stromal crosstalk." (PMID 30352967, 2018). "This may explain why there was no significant statistical association of miR-31 and c-MET immunopositivity in our tumor samples." (PMID 29463215, 2018). "Due to the specific neuropilin-1/MET co-distribution on cells lining such abnormal tumor vessels in contrast to normal endothelial cells, rhodocetin-αβ formed the necessary trimeric signaling complex of rhodocetin-αβ-MET-neuropilin-1 only in these abnormal tumor vessels." (PMID 29854288, 2018). "These open issues led us to study about whether MET activation under hypoxia inducing a tumor-invasive switch in HCC is a mechanism of refractory to antiangiogenic treatment and whether this form of evasive resistance can be prevented or reversed by inhibition of MET in HCC." (PMID 29712569, 2018). "Our observations provide strong evidence that TAS-115 can serve as a multiple tyrosine kinase inhibitor which can impede c-MET and PDGFRα signalling and may offer the distinct clinical advantages even when used as a monotherapy for patients with SS tumours driven by either c-MET or PDGFRα pathways." (PMID 28511645, 2017). "Association with clinical and pathological features in primary tumor, MET copy number gains in the context of metastatic spread and initial in-vitro data indicating that MET-signaling acts as mediator of antiangiogenic therapy, suggest a biologic relevance of MET signaling in ccRCCs." (PMID 27894094, 2017). "In particular, the combination treatment of TAK-701 and gefitinib markedly reduces tumor growth in HCC827-HGF cell xenografts, a human NSCLC cell line with an activating EGFR mutation and HGF overexpression; this treatment also inhibited phosphorylation of c-MET, EGFR, ERK, and Akt." (PMID 28817103, 2017). "Furthermore, HGFR expression and MET copy numbers should not only be assessed in the primary tumor, but also, maybe even more important, in recurrences or metastasis to guide anti-MET therapy in ccRCC patients." (PMID 27894094, 2017). "Additionally, MET amplification was rarely found in pre-treatment tumor tissues." (PMID 28002810, 2017). "Furthermore, administration of tracers based on the HGF ligand such as 64Cu-HGF, as well as the bivalent antibody DN30, might have the unwanted result of stimulating tumour growth by activating c-MET." (PMID 28315949, 2017).
tumor (continued). "HGF interacts with c-MET via an autocrine and/or paracrine signaling loop and participates in a variety of biological responses, such as embryonic development, epithelial branching morphogenesis, postnatal organ regeneration, wound healing, and tumor development." (PMID 28817103, 2017). "Our results suggest that 3rd generation TKIs may retain activity against T790M-positive tumors in some patients, even in the presence of MET activation, which may be due to the spatial heterogeneity of resistance mechanisms rather than co-existence of 2 resistance mechanisms in the same tumor cells." (PMID 29285237, 2017). "Therefore, LECT2 could inhibit both tumor growth and metastasis by simultaneously targeting MET and VEGFR2 in HCC patients." (PMID 27507763, 2016). "However, because the transforming potential of mutant MET appears to depend on the presence of HGF, it is possible that inhibitors of HGF activation may block tumor progression in cancers that are driven by mutant MET." (PMID 27121052, 2016). "In addition, the receptor tyrosine kinase c-MET, known to exert a major role in tumor formation and progression, has been shown to be induced in hypoxic cancers in general, and in advanced or androgen-receptor-independent prostate cancer in particular, especially in bone metastases." (PMID 26762579, 2016). "The results showed that ddPCR could determine the MET status in tumor samples." (PMID 26765781, 2016). "MET (mesenchymal-epithelial transition factor) proto-oncogene on chromosome 7q31 encodes for a receptor tyrosine kinase (RTK) and regulates a variety of downstream signaling pathways that initiate gene expression involved in promoting tumor growth, survival, angiogenesis, invasion and metastases." (PMID 27421137, 2016). "Thus, acquiring fresh tumor biopsies for FISH analysis may be needed to identify patients with MET amplification." (PMID 26879245, 2016). "A selective effect of MET-T1010I as compared to wild type MET on cell invasion both in-vitro and in-vivo suggests that the MET-T1010I SNP may alter tumor pathophysiology and should be considered as a potential biomarker when implementing MET targeted clinical trials." (PMID 25605252, 2015). "Based on our findings, NSCLC patients with lower EGFR/MET relative ratios, possibly reflecting a requirement for both signaling pathways to sustain tumor growth, may be the ideal patient subgroup to benefit from combined EGFR and MET inhibition compared to single agent therapy." (PMID 26439803, 2015). "Thus, nearly all of MET expressing tumor samples were also positive for MET expression." (PMID 26215852, 2015). "Finally, we show that in GBM with EGFR amplification (EGFRamp), long-term exposure to erlotinib induces adaptive tumor growth that involves MET pathway activation, supporting the use of a combination of both inhibitors to more effectively control GBM progression." (PMID 26381735, 2015). "Several studies have reported that ALK or MET over-expression and constitutive kinase activation correlate with advanced stage and may be predictive of poor clinical outcome in several neoplasia, such as neuroblastoma, gastrointestinal carcinoma and non-small-cell lung cancer." (PMID 26445453, 2015). "In summary this report supports that the aberration in Cbl-mediated negative regulation of MET can indeed result in MET protein overexpression and subsequent addiction of tumor cells to MET signaling and may serve as an actionable driver mutation in a subset of GI malignancies." (PMID 26375439, 2015). "However, HGF derived from the tumor microenvironment has recently been shown to protect MET-amplified cells, otherwise sensitive to MET inhibitors, suggesting a role for the ligand in the resistance to anti-MET therapy, and providing the basis for the use of HGF-neutralizing drugs." (PMID 28548076, 2014).
tumor (continued). "Microdissection of tumor cell nests from the tumor-invading front revealed that the levels of RNA transcripts for MET/HIF were higher than in the center of the tumor, thus, suggesting that HIF-1 may be one of the factors that contribute to the increased MET transcription in PTC." (PMID 28548071, 2014). "Moreover, miR-206 could promote myogenic differentiation and block tumor growth in xenografted mice by downregulating the product of the MET proto-oncogene: Met tyrosine-kinase receptor." (PMID 24855559, 2014). "High-MET mRNA was associated with older age (P = .002), larger tumor size (P = .006), LN metastasis (P = .014), lymphatic invasion (P<.001), increased number of metastatic lymph nodes (P<.001), distant metastasis (P = .001), and higher TNM stage (P<.001) when compared to low-MET mRNA." (PMID 25364819, 2014). "Thus, c-MET signals have bearing for E98 tumor cell migratory potential as well." (PMID 23484006, 2013). "Anti-MET antibody is believed to be bivalent (i.e., antagonistic and agonistic effects), but the technology of monovalent antibody (i.e., antagonistic effect only) may support the anti-tumor therapy." (PMID 23296269, 2013). "Moreover, MET is expressed by endothelial cells, and can be involved in tumor angiogenesis." (PMID 22973229, 2012). "In addition, MET transcription is induced by environmental cues, such as growth factors secreted by the adjacent stroma, including HGF itself, or by oxygen deficiency, or hypoxia, a frequent occurrence in the rapidly growing tumor tissue." (PMID 22973229, 2012). "The HGF/c-MET pathway might play a key role in prostate carcinogenesis and tumour progression." (PMID 22110593, 2011). "The c-Met protein is expressed mostly in in mammalian tissues and plays an important role in different cellular processes; its ligand is the HGF (Hepatocyte Growth Factor), known also as Scatter Factor (SF) and c-MET over-expression or inactivation is implicated in different tumoral disease." (PMID 19384429, 2007). "Our findings here differ from the recent report of the induction of c-MET overexpression by hypoxia, a cellular state that is conceivably more prominent within the tumour core than along the peripheral expanding tumour front juxtaposing the adjacent lung alveoli." (PMID 17667909, 2007). "Tumor cell killing assays in co-cultures with PBMCs showed that the Db-TriTE performed equally well to the bispecific control, taFv-EGFR on c-MET-/EGFR+ SW480 cells." (PMID 41552759, 2026). "In C1-GBM, key tumor driver genes included BIRC3 (Baculoviral IAP Repeat Containing 3), MET (MET Proto-Oncogene, Receptor Tyrosine Kinase), COL1A1 (Collagen Type I Alpha 1 Chain), CR1 (Complement C3b/C4b Receptor 1), and IL7R (Interleukin 7 Receptor)." (PMID 41614933, 2026). "Receptor tyrosine kinases such as c-MET and HER2 are clinically relevant targets involved in tumor progression and resistance mechanisms." (PMID 41901229, 2026). "The EVOO PPRF was more effective than pure OC in inhibiting the p-c-MET tyrosine 1349 in HCT-116 cells and collected primary tumors, justifying its preference for the tumor-motility suppressive effects." (PMID 39940255, 2025). "Interestingly, an additional missense variant not detected in the tumor WGS was identified in MET (NM_000245.4: c.2908C>T, p.R970C), which might represent a sub-clone." (PMID 40386554, 2025). "Similar oncogenic roles are observed in MET-amplified diffuse gastric cancer, where PLEKHA5 silencing inhibits the growth of MET inhibitor-resistant tumor cells." (PMID 40356756, 2025). "On the other hand, c-MET is a receptor tyrosine kinase that is often dysregulated in cancers, including HNSCC, and its deregulation contributes to tumor progression, metastasis, and resistance to therapy." (PMID 40430804, 2025).
tumor (continued). "Based on the percentage of samples with a T/N expression ratio higher than 2, c-MET and CEA exhibited the greatest differential contrast after nCRT, highlighting their potential as targets for molecular tumor-guided imaging in RC." (PMID 40563608, 2025). "The other patient showed a MET amplification by FISH, with a MET to centromere ratio of > 2 as determined in nuclei of 50 tumor cells." (PMID 40878657, 2025). "The results of subsequent western blotting experiments indicated that c‐MET and AKT/ERK phosphorylation levels in the tumour were significantly decreased after the c‐MET inhibitor was applied." (PMID 41190648, 2025). "These miRNAs also exhibited tumor-suppressive roles by negatively correlating with key oncogenes such as FN1 and MET." (PMID 40647442, 2025). "Tumor-derived EVs are especially rich in oncoproteins (eg, mutant KRAS, MET) and proteases (MMP2/9), which contribute to invasive and metastatic properties." (PMID 40959053, 2025). "Neuropathiazol, a neurogenic inducer, was found to bind MET and upregulate NeuroD1 via the PI3K/Akt pathway, enhancing transdifferentiation and inhibiting tumor growth." (PMID 41225636, 2025). "Amivantamab acted by blocking the vital oncogenic pathways regulated by MET and EGFR, further recruiting immune cells to the tumor and enhancing tumor killing through mechanisms like ADCC." (PMID 40277763, 2025). "Immunohistochemical analysis of 3D heterotypic tumor spheroids confirmed that both individual and combined treatment with TAS-115 and DOXO reduced the expression of c-MET, p–c-MET, and p-mTOR, a key node in the PI3K/Akt/mTOR pathway." (PMID 41289612, 2025). "In line with the in vitro tumor-targeting studies, AS1411 demonstrated more pronounced fluorescence signals and sustained accumulation at the tumor sites compared to SL1, indicating a greater surface expression of NCL than c-MET on OS cells." (PMID 39744222, 2025). "Preclinical and early-phase clinical trials have demonstrated the potential of c-MET-CAR-T cells to effectively target and kill tumor cells, with encouraging signs of tumor control and immune response at treatment sites." (PMID 40281554, 2025). "that integrated the EGFR inhibitor erlotinib with the MET inhibitor PF04217903 in a c-SRC (Cellular Sarcoma Kinase) expressing cell line demonstrated a significant reduction in cell viability and tumor volume." (PMID 40881676, 2025). "OC effectively suppressed the MBD p-c-MET tyrosine 1356 more than PPRF, which suggests a preference for tumor growth/survival inhibition over the use of crude PPRF." (PMID 39940255, 2025). "Given its importance in tumor progression and therapeutic resistance, the HGF/c-MET axis has emerged as a potential target for cancer treatment." (PMID 40304568, 2025). "H-scores of CEA, EpCAM, c-MET, and EGFR were compared between tumor and adjacent normal epithelial tissues using pre- and post-treatment specimens." (PMID 40563608, 2025). "The inhibitory effect on tumor growth is further enhanced by co-inhibition of FGFR, EGFR, and MET, which reduces activation of ERK and Akt." (PMID 41516252, 2025). "TKIs such as cabozantinib, axitinib, and lenvatinib target critical pathways in angiogenesis, tumour growth, and metastasis, including VEGFR, MET, and AXL pathways." (PMID 40957947, 2025). "OC’s anti-cancer effects arise from its ability to selectively destabilize cancer cell lysosomes, inhibit oncogenic signaling (c-MET/STAT3), and disrupt tumor microenvironment support." (PMID 40564985, 2025). "Genetic alterations (mutations, amplifications, etc.)or c-MET overexpression drive aberrant MET/HGF signaling, promoting tumor initiation, metastasis, and drug resistance across cancers." (PMID 41353695, 2025). "CAFs are known to influence tumor cell behavior through pathways such as those elicited by e.g. IL-6, HGF/MET, IFNβ1 and certain microRNAs." (PMID 40042717, 2025).
tumor (continued). "After a durable clinical and radiographic response, the progression biopsy demonstrated loss of MET amplification together with emergent HGF p.G401A and NF1 p.M546L, pointing to ligand reactivation and RAS/MAPK bypass as hypothesis-generating routes of escape in this tumor." (PMID 41268440, 2025). "H11, a novel c-MET degrader, induces c-MET ubiquitination-proteasome degradation and demonstrates anti-tumor activity while overcoming drug resistance." (PMID 40606973, 2025). "•In patient-derived tumor organoid models, FER controls MET and EGFR oncogenic signaling required for invasion in 3D Collagen-I extracellular matrix." (PMID 41115375, 2025). "HGF aberrant expression by CRC activates c-MET, triggering downstream PI3K/AKT and RAS/RAF/MAPK pathways promoting tumor growth, survival, motility and angiogenesis." (PMID 39940255, 2025). "A multi-institutional analysis of repeat tumor or plasma biopsies from patients with RET fusion-positive NSCLC treated with selpercatinib and pralsetinib identified the emergence of MET amplification (15%) and KRAS amplification in one case each." (PMID 39850629, 2025). "Cabozantinib, a small-molecular-weight tyrosine kinase antagonist, shows specific inhibition of several receptors essential in tumor growth and metastasis, such as VEGFR1, VEGFR2, VEGFR3, MET, and AXL." (PMID 40699663, 2025). "The multi-kinase inhibitor cabozantinib exerts potent anti-HCC effects by suppressing c-MET and ERK activity, leading to reduced PKM2 expression and impaired tumor angiogenesis." (PMID 41169372, 2025). "Sequential tissue sections from biopsy samples were stained for CEA, EpCAM, c-MET, and EGFR, with tumor expression levels quantified using the H-score method." (PMID 40563608, 2025). "MET protein, RNA-ISH and DNA-ISH were performed on the pre-treatment metastasis biopsies or archival tumour tissues in the 36 patients (100%) recruited to the dose expansion cohort." (PMID 40211189, 2025). "Foretinib is an oral multi-kinase inhibitor targeting MET, ROS, RON, AXL, TIE-2, and VEGFR, which has demonstrated good anti-tumor activity and tolerability in a phase I/II single-arm study." (PMID 40376263, 2025). "Moreover, the association between MET overexpression and improved survival was independent of PD-L1, suggesting that MET overexpression may influence the tumor immune microenvironment through mechanisms beyond the PD-L1 pathway." (PMID 41375002, 2025). "AXL is known to be involved in tumor cell growth, metastasis, and drug resistance and has been shown to bind to members of the EGFR and HER families, including MET, to promote EGFR signaling and contribute to EGFR-TKI resistance." (PMID 40224214, 2025). "For example, synthetic miR-34a mimics have shown potent anti-tumor activity in preclinical models: they inhibit epithelial–mesenchymal transition (EMT) and induce apoptosis by targeting BCL2 and MET, among other oncogenes." (PMID 41226828, 2025). "These miRNAs regulate tumour cell proliferation, migration, and immune evasion by participating in signalling pathways such as PI3K/AKT, MET/AXL, and Wnt/β-catenin." (PMID 41195336, 2025). "As expected, simultaneous inhibition of EGFR and MET with Afatinib and Capmatinib in the presence of EGF and HGF, results in an almost complete cessation of tumor cell invasion in 3D." (PMID 41115375, 2025). "We further examined the expression and phosphorylation of the MET, PI3K, and AKT proteins in tumor tissues treated with Neuropathiazol or gemcitabine via Western Blotting." (PMID 41225636, 2025). "We also excluded five markers that showed expression in both tumor subtypes (AGR2, SNAI2, KRT6A, MET, SLC16A3)." (PMID 39935174, 2025). "In this study, expression levels of key apoptotic and survival-related genes, including Bax, Bcl-2, Caspase-3, c-MET, and HGF in response to TAS-115 and its combination with DOXO in 3D tumor spheroids." (PMID 41289612, 2025).